MIR3936HG (MIR3936 host gene)
Synonyms: LOC553103; SLC22A5-AS1
Gene: Long non-coding RNA gene on chromosome 5 (132,311,285 to 132,370,170, reverse strand). Ensembl gene ENSG00000233006.
Diseases named in the same sentence as MIR3936HG in open-access papers:
MIR3936HG is named in the same sentence as 9 diseases in open-access papers, as found by Europe PMC text mining. Sharing a sentence is not in itself a finding about the gene and the disease.
MIR3936HG shares sentences with these, for which no sentence is quoted: cancer (2 papers); colon cancer (1); colorectal cancer (1); esophageal cancer (1); gastric carcinoma (1); hepatocellular carcinoma (1); myeloma (1); non-small cell lung carcinoma (1); ovarian carcinoma (1).